EGFR (epidermal growth factor receptor)
Diseases named in the same sentence as EGFR in open-access papers (continued):
Sharing a sentence is not in itself a finding about the gene and the disease.
colorectal cancer (continued). "Recently, some driver proteins in these pathway, for example the MYC and EGFR antagonists, were also being developed as therapeutic agents for prostate and colorectal cancer." (PMID 30065750, 2018). "In summary, NDAT inhibited the constitutive or inducible activation of PI3K in colorectal cancer cells, which plays an important role to knock down the sialylation of EGFR to inhibit cancer cell proliferation." (PMID 30187356, 2018). "The HER family has been a focus of attention in colorectal cancer since the development and licensing of the EGFR monoclonal antibodies panitumumab and cetuximab." (PMID 29254887, 2018). "Here, we tested the effect of the EGFR antibody cetuximab in different sequential combinations with oxaliplatin on the growth of colorectal cancer cells in vitro and in vivo." (PMID 30410004, 2018). "For example, (i) radiation combined with EGFR blockade inhibited tumour proliferation, increased apoptosis, prolonged G2/M arrest and significantly enhanced DNA injury in colorectal cancer." (PMID 29860480, 2018). "The gain-of-function KRAS mutations, in particular, are responsible for bypassing EGFR upstream signals resulting in poor response to anti-EGFR therapies in 30–40% of colorectal cancer." (PMID 29304017, 2018). "Overexpression of TGFα contributes to resistance to EGFR inhibitor cetuximab in colorectal cancer cells." (PMID 30034618, 2018). "Antitumor efficacy of CTX in combination with conventional chemotherapy has been proven in various EGFR-expressing malignancies like colorectal cancer, head and neck cancers and recurrent NPC." (PMID 29580204, 2018). "Other studies have confirmed the consistent heterogeneity of colorectal cancers at the level of primary tumors and synchronous metastases: this heterogeneity was present before and after anti-EGFR therapy." (PMID 29652830, 2018). "Signaling through the Epidermal Growth Factor Receptor (EGFR) pathway is a common event in cancer development, with activating mutations in KRAS, NRAS and BRAF occurring in approximately 50% of colorectal cancer (CRC) patients." (PMID 29568398, 2018). "The difference in severity of oral mucositis between different anti-epidermal growth factor receptor (EGFR) antibodies combined with cytotoxic drugs in colorectal cancer is unclear." (PMID 30290786, 2018). "Here, we assessed the efficacy of EGFR mAbs in simultaneous and sequential combinations with oxaliplatin in a panel of colorectal cancer cell lines with different genetic backgrounds (wild-type or mutant for KRAS or BRAF)." (PMID 30410004, 2018). "Among various mechanisms of resistance to anti-EGFR agents, the frequency of RAS mutations, which serve as the major predictive biomarker of anti-EGFR treatments in colorectal cancer, was found to be low in gastric cancer patients." (PMID 30321186, 2018). "For example, Bardelli and colleagues have demonstrated that KRAS mutant sub-clones of colorectal cancers are more sensitive to withdrawal of an EGFR monoclonal antibody-based regimen such as cetuximab than are their wildtype counterparts." (PMID 29491834, 2018). "A total of 75 colorectal cancer outpatients treated with an anti-EGFR antibody combined with FOLFOX, FOLFIRI, or 5-FU/leucovorin as the first- to third-line treatment were included." (PMID 30290786, 2018). "(E) Kaplan-Meier curves comparing gene mutation status and gene copy number for EGFR and MLH1 alterations in colorectal cancer." (PMID 30526857, 2018). "This has been shown for colorectal cancers, with much of the research performed in anti-EGFR resistance." (PMID 30128304, 2018). "One pathway that appears to be perturbed is the EGFR signaling pathway, one with critical importance in colorectal cancer development." (PMID 29718933, 2018). "In colorectal cancer cells with mutated KRAS, treatment with cetuximab (anti-EGFR mAbs) or regorafenib (oral multikinase inhibitor) alone does not produce more than 22% of apoptosis after 24 h of treatment." (PMID 30382908, 2018).
colorectal cancer (continued). "Accordingly, combined BRAF and EGFR inhibition showed synergistic efficiency in colorectal cancer cells in vitro and in vivo." (PMID 29192388, 2018). "To analyze the influence of Fas survival pathways on the EGFR signaling in cancer, we examined the EGF-induced activation of EGFR in two KRAS-mutated, cetuximab-resistant colorectal cancer cells, SW480 and HCT116." (PMID 30127519, 2018). "Next, we analyzed the cell type in which EGFR is required to induce OS formation, as we and others have recently shown that EGFR expression in myeloid cells is essential for the development of hepatocellular and colorectal cancer." (PMID 30361264, 2018). "In our study, we identify the autophagy initiation through anti-EGFR monoclonal antibodies and checkpoint inhibitors in colorectal carcinoma cell lines according to microsatellite status." (PMID 30427914, 2018). "In colorectal carcinoma, KRAS-mutation indicates irresponsiveness to EGFR-targeted treatment and showed high FDG-PET uptake in multiple studies." (PMID 29732009, 2018). "Especially in colorectal cancer, however, where the KRAS mutation status is crucial for the decision of anti-EGFR treatment, there is increasing evidence for a paradigm shift." (PMID 28674438, 2017). "Studies also suggest that ADCC activity is one of the modes of therapeutic action of cetuximab against colorectal cancer that targets the epidermal growth factor receptor (EGFR)." (PMID 29295568, 2017). "Tissue microarray assays demonstrated a correlation between RHBDD1 and EGFR in colorectal cancer patients." (PMID 28445956, 2017). "Alternatively, ARRB1 has also been shown to enhance the activation of EGFR in colorectal cancers leading to increased mitogenic signaling." (PMID 28596572, 2017). "We detected credible resistance mutations in all of the genes previously found clinically to confer resistance to EGFR therapy in colorectal cancer." (PMID 28179366, 2017). "This supports miR-31-3p as a promising predictive biomarker for anti-EGFR therapy in KRAS WT advanced colorectal cancer." (PMID 29212194, 2017). "A study on colorectal cancer, however, demonstrated that cellular EGFR localization was unrelated to clinicopathological parameters or patient outcome." (PMID 28367377, 2017). "In vitro experiments revealed that ciRS-7 inhibited miR-7 activity and activated the EGFR/RAF1/MAPK pathway, which linked ciRS-7 activity with colorectal cancer progression and aggressiveness." (PMID 29349062, 2017). "Target EGFR therapeutic monoclonal antibodies, namely cetuximab, panitumumab and some small tyrosine kinase inhibitors (TKIs), have gotten approval in treating colorectal cancer." (PMID 28445134, 2017). "Here we summarize some of the main studies correlating specific ncRNAs with sensitivity/resistance to chemotherapy, anti-VEGF therapy, anti-EGFR therapy and immunotherapy in colorectal cancer (CRC)." (PMID 28714940, 2017). "Our previous study showed that RHBDD1 can activate the EGFR signaling pathway to promote colorectal cancer growth." (PMID 28445956, 2017). "The anti-EGFR antibody cetuximab, approved for treatment of EGFR expressing colorectal cancers, competitively blocks the binding of EGF to its receptor." (PMID 28402937, 2017). "In a study that evaluated epidermal growth factor receptor (EGFR) expression in 386 resected colorectal cancers, 74% of tumors showed concordance of EGFR expression between tumor center and rim." (PMID 28456115, 2017). "For example, RAS pathway mutations have been detected by ctDNA as a mechanism of resistance in colorectal cancer to anti-EGFR therapies." (PMID 28685150, 2017). "Our recent finding that sialidase NEU3 actively promotes EGFR autophosphorylation and is responsible for the increased viability of colorectal cancer cells prompted us to investigate the effect of this sialidase overexpression in NSCLC." (PMID 29088281, 2017).
colorectal cancer (continued). "The combined EGFR and BRAF inhibition decreases cell proliferation and triggers apoptosis of BRAF-mutated colorectal cancer cell lines and xenografts." (PMID 29312543, 2017). "Gefitinib (GEF, brand name Iressa), an orally active EGFR inhibitor, has been approved for several types of tumor including colorectal cancer." (PMID 26461472, 2017). "A key observation is that the vast majority of colorectal cancer expresses EGFR and the inhibition of BRAF triggers the activation of EGFR." (PMID 29312543, 2017). "Cetuximab (IgG1 subtype) is an anti-EGFR monoclonal antibody approved by the Food and Drug Administration USA for colorectal cancer and head and neck squamous cell cancer." (PMID 28467975, 2017). "EGFR-targeted therapeutics has indicated clinical success in the treatment of several types of cancers, including colorectal cancer." (PMID 26461472, 2017). "Of the 109 patients with colorectal cancer treated with anti-EGFR therapeutics, 50 (46%) received cetuximab and 59 (54%) received panitumumab." (PMID 28147317, 2017). "Here we showed that the addition of the COX-2 inhibitor celecoxib improved the antitumor efficacy in colorectal cancer (CRC) of the monoclonal anti-EGFR antibody cetuximab." (PMID 28423516, 2017). "We screened 51 colorectal cancer cell lines with a concentration range of the EGFR monoclonal antibody Cetuximab and assessed viability after 6 d." (PMID 28179366, 2017). "By contrast, NRG1 was overexpressed in only 1% of colorectal cancers, a tumor type where anti-EGFR monoclonal antibodies (cetuximab and panitumumab) are currently approved for use." (PMID 28723928, 2017). "Low EZH2 expression was significantly associated with a shorter PFS and OS in patients with KRAS (codon 12/13) wild-type group colorectal cancer treated with anti-EGFR therapeutics." (PMID 28147317, 2017). "Approximately 40–45% of colorectal cancers harbor KRAS mutations, and mutation status is predictive of resistance to anti‐EGFR‐based targeted therapy in patients with metastatic colorectal cancer receiving cetuximab or panitumumab." (PMID 28173629, 2017). "The epidermal growth factor receptor (EGFR) is a cell surface protein that has become an important therapeutic target in colorectal cancer (CRC)." (PMID 29183279, 2017). "We recently suggested that miR-31 regulates the signaling pathway downstream of epidermal growth factor receptor (EGFR) in colorectal cancer." (PMID 28147317, 2017). "GEF has shown promising activity in a minority of colorectal cancer patients with high EGFR signaling activity." (PMID 26461472, 2017). "Further functional analysis is required for clarifying the regulatory role of EZH2 in the signaling pathway downstream of EGFR in colorectal cancer." (PMID 28147317, 2017). "In clinic, cetuximab, an anti-EGFR antibody, improves treatment outcomes in colorectal cancer (CRC)." (PMID 28301591, 2017). "Our results are in contrast with those observed in colorectal cancer cells, where a significant increase in cell viability was observed in an EGFR-hyper-stimulated cell line upon NEU3 overexpression." (PMID 29088281, 2017). "EGFR overexpression has been observed in many cancers, such as head and neck cancer, pancreatic cancer, and colorectal cancer." (PMID 28445956, 2017). "The CO-17 study, which compared treatment with cetuximab and best supportive care (BSC) to BSC alone in patients with metastatic EGFR-positive colorectal cancer, revealed that EREG expression levels were positively correlated with cetuximab treatment efficacy." (PMID 26884344, 2017). "In colorectal cancer patients, it has been shown that activating mutations of KRAS – an EGFR downstream effector - predicts resistance to anti-EGFR monoclonal antibodies therapy in metastatic patients." (PMID 28881811, 2017).
colorectal cancer (continued). "This low response rate is due in part to differential expression/activation of EGFR in colorectal cancer compared to melanoma, ultimately leading to MAPK pathway activation and thereby circumventing BRAF inhibition." (PMID 27999210, 2017). "These agents should target biomarkers known to be overexpressed in colorectal cancer such as epidermal growth factor receptor (EGFR)." (PMID 28157706, 2017). "Recently, HER2, EGFR, PDGFRA and MAP2K1 mutations and FGFR1 amplifications have been identified as plausible innate resistance mechanisms to EGFR targeted therapy in colorectal cancer, as well as ALK, FGFR2, NTRK1/2 and RET kinase addition." (PMID 28032592, 2017). "On the other hands, both mutations in KRAS and BRAF have been clearly demonstrated to predict resistance to EGFR-directed therapy in colorectal cancer." (PMID 29312543, 2017). "Panitumumab, another anti-EGFR antibody used for treating patients with colorectal cancer, showed a comparable synergistic effect as cetuximab in an in vivo experiment." (PMID 28287083, 2017). "Nevertheless, the possible correlation between miR-193a-3p expression and the clinical outcome from anti-EGFR therapy in patients with colorectal cancer further support a role of miR-193a-3p in the EGFR-related signaling pathway." (PMID 29115941, 2017). "As demonstrated, ciRS-7 blocked miR-7 activity and positively regulated the expression of EGFR and IGF-1R oncogenes, indicating that the ciRS-7/miR-7 axis was associated with colorectal cancer progression." (PMID 29349062, 2017). "As other pathway, Liska and colleague have reported that hepatocyte growth factor (HGF)-activating c-MET rescued EGFR inhibition in colorectal cancer cells." (PMID 28642617, 2017). "Recently, the effect of AREG on the prognosis and treatment efficacy of colorectal cancer patients receiving the anti-EGFR agent was investigated." (PMID 26884344, 2017). "Anti-EGFR monoclonal antibody panitumumab (IgG2 subtype), on the other hand, is approved for treatment of colorectal cancer." (PMID 28467975, 2017). "cetuximab, an epidermal growth factor receptor inhibitor, is a targeted therapeutic regimen of colorectal cancers." (PMID 29390545, 2017). "Equally attractive is combined treatment of miR-133b and cetuxima can intensify suppression effect on the growth and invasion of colorectal cancer cells by modulating EGFR." (PMID 28422730, 2017). "Accordingly, one current strategy to overcome colorectal cancer cell resistance to EGFR inhibitors is by inhibiting RAS pathway." (PMID 26461472, 2017). "The epidermal growth factor receptor (EGFR) is recognized as an important player in colorectal cancer (CRC) initiation and progression." (PMID 28869531, 2017). "Targeting EGFR has been extensively studied in oncology, and monoclonal antibodies (e.g., cetuximab) against the extracellular domain of the EGFR have been developed as treatments against cancers, including colorectal cancer." (PMID 28800074, 2017). "The same effect of macrophage infiltrate on EGFR activation was also seen in a colorectal cancer xenograft." (PMID 28166195, 2017). "As proof of concept, we used this screen in the setting of an EGFR therapy and colorectal cancer, a disease in which response to such therapy is invariably followed by the acquisition of resistance." (PMID 28179366, 2017). "EGF was used as cell-cycle inducer since EGFR signaling promoted cell-cycle progression in colorectal cancer." (PMID 29108242, 2017). "In metastatic/advanced colorectal cancer, a patient’s suitability for treatment with anti-EGFR monoclonal antibodies is determined by the presence of mutations in KRAS and/or NRAS." (PMID 29029407, 2017). "It has been reported that KRAS and BRAF mutations were negatively correlated with the response to targeting EGFR treatment in lung and colorectal cancers." (PMID 28556791, 2017).
colorectal cancer (continued). "This meta-analysis was performed to determine the optimal use of anti-EGFR mAb in the treatment of metastasized colorectal cancer (mCRC)." (PMID 28695301, 2017). "Our lab previously found that RHBDD1 is overexpressed in colorectal cancer tumors, and EGFR was often overexpressed in many cancers." (PMID 28445956, 2017). "The concomitant inhibition of EGFR and other signaling pathways has been proven effective in colorectal cancer cells." (PMID 28423516, 2017). "The specific objective was to evaluate the effect of MAG-EPA on tumor growth and VEGFR and EGFR activation pathways using an in vitro model of human colorectal cancer cell line HCT116 and an in vivo mouse model of HCT116 xenograft." (PMID 28869531, 2017). "Anti-epidermal growth factor receptor (EGFR) therapy has been found to be more effective against left-sided colorectal cancer (LCRC) than right-sided colorectal cancer (RCRC)." (PMID 29212173, 2017). "High miR-31-3p expression is associated with inferior outcomes in KRAS wild-type (WT) advanced colorectal cancer patients treated with anti-EGFR therapy." (PMID 29212194, 2017). "Rather, around 50% of colorectal cancers have been reported to contain EGFR gene amplification, with a three- to five-fold increase in copy number." (PMID 28513565, 2017). "Tumor response of patients with KRAS/BRAF-wild-type colorectal cancer who received anti-EGFR therapy based upon the miR-193a-3p expression status." (PMID 29115941, 2017). "Recently, two studies of plasma DNA sequencing in colorectal cancer patients undergoing treatment with EGFR monoclonal antibodies jointly identified the first MAP2K1 codon K57 resistance mutations (p.K57T and p.K57N)." (PMID 28179366, 2017). "Currently, the most clinically significant mutated genes in colorectal cancer are KRAS, NRAS and BRAF as these genes provide information on a patients’ prognosis and their suitability for anti-EGFR therapies." (PMID 29029407, 2017). "The prognosis of colorectal cancer has been recently improved due to advances in chemotherapy and target‐specific therapies such as anti‐epidermal growth factor receptor (EGFR) antibody therapy." (PMID 28544335, 2017). "During the follow-up study of the 109 patients with colorectal cancer treated with anti-EGFR therapeutics who were eligible for survival analysis, 64 patients died (all deaths were confirmed to be attributed to colorectal cancer)." (PMID 28147317, 2017). "The epidermal growth factor receptor (EGFR) signaling pathway was the obvious next target due to its deep association with tumor development in various cancer types, including lung and colorectal cancer." (PMID 28841181, 2017). "The detection of KRAS and BRAF mutations is a crucial step for the correct therapeuticapproach and predicting the epidermal growth factor receptor (EGFR)-targeted therapyresistance of colorectal carcinomas." (PMID 28580315, 2017). "The KRAS gene is mutated in about 40 % of colorectal cancer (CRC) cases, which has been clinically validated as a predictive mutational marker of intrinsic resistance to anti-EGFR inhibitor (EGFRi) therapy." (PMID 27756306, 2016). "ET-1 provided a growth stimulus to colorectal cancer cells; the signal was also propagated via the transactivation of the epidermal growth factor receptor (EGFR)." (PMID 27490540, 2016). "Five of these 20 colorectal cancer patients (25.0%) received anti-EGFR therapy, whereas the rest (15 patients) received other available therapies." (PMID 26968814, 2016).